DOHH (deoxyhypusine hydroxylase)
Description:
Catalyzes the hydroxylation of the N(6)-(4-aminobutyl)-L-lysine intermediate produced by deoxyhypusine synthase/DHPS on a critical lysine of the eukaryotic translation initiation factor 5A/eIF-5A. This is the second step of the post-translational modification of that lysine into an unusual amino acid residue named hypusine. Hypusination is unique to mature eIF-5A factor and is essential for its function (By similarity).
Synonyms: hDOHH; HLRC1; MGC4293; NEDMVIC
Tractability: Small molecule: a structure with a bound ligand is known. PROTAC: ubiquitination databases record sites on it; its protein half-life has been measured; a small molecule that binds it is known.
Target class: Enzyme; Oxidoreductase
Gene: Protein-coding gene on chromosome 19 (3,490,821 to 3,500,936, reverse strand). Ensembl gene ENSG00000129932.
Subcellular location (Human Protein Atlas): Cytosol; Nucleoli; Nucleoplasm
Pathways (Reactome):
Metabolism of proteins: Hypusine synthesis from eIF5A-lysine
Gene Ontology:
Molecular function: deoxyhypusine monooxygenase activity; iron ion binding; protein binding
Biological process: peptidyl-lysine modification to peptidyl-hypusine
Cellular component: cytosol
Genetic constraint (gnomAD): Loss-of-function variants: 16 observed, 14.17 expected, observed/expected ratio (o/e) 1.13, 90% interval 0.76 to 1.69. The synonymous counts are far from expectation, so gnomAD's model fits this gene poorly and the ratio says little. Missense variants: 460 observed, 371.49 expected, observed/expected ratio (o/e) 1.24, 90% interval 1.15 to 1.34. Synonymous variants: 233 observed, 174.96 expected, observed/expected ratio (o/e) 1.33, 90% interval 1.2 to 1.48.
Homologues: Orthologues: chimpanzee DOHH (99% identical), macaque DOHH (98% identical), guinea pig DOHH (87% identical), dog DOHH (87% identical), mouse Dohh (85% identical), rat Dohh (83% identical), pig DOHH (68% identical).
Diseases named in the same sentence as DOHH in open-access papers:
DOHH is named in the same sentence as 21 diseases in open-access papers, as found by Europe PMC text mining. Sharing a sentence is not in itself a finding about the gene and the disease. The quoted sentences say what the papers report.
glioblastoma (5 papers, 2012 to 2025). The most malignant astrocytic tumor (WHO grade IV). "For instance, DOHH is overexpressed in glioblastoma, and its inhibition prolonged survival in mouse models for this disease." (PMID 39937781, 2025). "Here we report that eIF-5A as well as the hypusine-forming enzymes deoxyhypusine synthase (DHS) and deoxyhypusine hydroxylase (DOHH) are highly overexpressed in glioblastoma patient samples." (PMID 22927971, 2012). "We found a general eIF-5A overexpression in tumor cells and an upregulation of DHS and DOHH in glioblastomas compared to tumors of grade I–III." (PMID 22927971, 2012). "Moreover, EIF5A, DHPS, and DOHH are also highly expressed in glioblastoma (GBM), the most aggressive primary brain tumor in adults with a poor prognosis (a 5-year survival: ~5%)." (PMID 39125743, 2024). "Interestingly, DHS and DOHH were significantly upregulated in glioblastoma samples compared to tumors of grade I–III." (PMID 22927971, 2012). "In glioblastomas, the relevant investigation reported an up-regulation of DHS, DOHH, and EIF5A1 in glioblastoma patient samples with different grades, and both inhibition of hypusination by GC7 or stable knockdown of DHS and EIF5A1 impaired the proliferation of glioma cells in vitro." (PMID 32368188, 2020).
prostate carcinoma (4 papers, 2014 to 2023). A carcinoma that arises from epithelial cells of the prostate gland. "It was shown that overexpression of miRNA-642 in prostate cancer cells resulted in reduced cell viability by targeting deoxyhypusine hydroxylase (DOHH) that regulates cell growth through the eukaryotic translation initiation factor." (PMID 37108073, 2023). "In prostate cancer cell lines, it has been reported that the microRNA-mediated repression of DOHH expression suppresses the cell-proliferative capacity." (PMID 36358254, 2022). "Using a similar approach we previously identified ErbB-2 and Deoxyhypusine hydroxylase (DOHH) as novel targets of miR-331-3p in prostate cancer." (PMID 24142150, 2014). "As a positive control for this assay we assessed the expression of DOHH, a validated miR-331-3p target in prostate cancer cells and found that DOHH expression was decreased in GBM cells following transfection of miR-331-3p (data not shown)." (PMID 24142150, 2014). "We and others identified several targets of miR-331-3p in prostate cancer cells, including ErbB-2, DOHH and KLK4." (PMID 24142150, 2014). "Additionally, inhibition of DOHH via mimosine is found to act in synergy with miR-331-3p and miR-642-5p that are targeting DOHH mRNA to inhibit cell growth in a prostate cancer cell model." (PMID 36511302, 2022).
developmental delay (3 papers, 2021 to 2023). "Further investigations are ongoing to determine the impact of other biallelic DOHH variants of unknown significance identified in a cohort of individuals with developmental delay." (PMID 34273022, 2022). "The three proteins eIF5A1, DHPS, and DOHH are highly conserved in eukaryotes and their pathogenic variants are collectively referred to as eIF5A1 and hypusination-related disorders that are characterized by global developmental delay, intellectual disability, facial dysmorphism, and microcephaly." (PMID 36848144, 2023).
malaria (2 papers, 2013 to 2016). Malaria is a serious and sometimes fatal disease caused by a parasite that commonly infects a certain type of mosquito which feeds on humans. "Here, we present the first successful cloning and expression of DOHH from P. vivax causing tertiary malaria." (PMID 23505486, 2013). "It was shown that pharmacological inhibition of the enzymes involved in this pathway, deoxyhypusine synthase (DHS) and the deoxyhypusine hydroxylase (DOHH), arrested the growth of malaria parasites." (PMID 27516964, 2016).
microcephaly (2 papers, 2022 to 2023). A congenital or acquired developmental disorder in which the circumference of the head is smaller than normal for the person's age and sex. "Rare biallelic loss of function variants in DOHH were identified in an 8 year old girl presenting a severe neurodevelopmental disorder with several symptoms such as hypotonia, dysmorphic features, and microcephaly, overlapping with those found in DHPS and EIF5A-related disorders." (PMID 34273022, 2022).
astrocytomas (1 paper, 2012). "Although eIF-5A, DHS and DOHH are highly conserved and likewise expressed in healthy tissues, their overexpression in aggressive astrocytomas and the enhanced responsiveness of GMB cells compared to normal astrocytes render these protein potential therapeutic targets in this intracranial neoplasm." (PMID 22927971, 2012).
cervical cancer (1 paper, 2023). A primary or metastatic malignant neoplasm involving the cervix. "For example, the knockdown of DOHH catalyzing hypusine formation significantly inhibited cervical cancer cell proliferation." (PMID 37047039, 2023).
glioma (1 paper, 2012). A benign or malignant brain and spinal cord tumor that arises from glial cells (astrocytes, oligodendrocytes, ependymal cells). "Using immunohistochemistry (IHC), we found elevated expression levels of DHS, DOHH and eIF-5A in 173 glioma samples with different grades." (PMID 22927971, 2012). "In order to establish an in vitro model for further functional characterisation of the hypusine modification in gliomas, we analysed the expression of eIF-5A, eIF-5A2, DHS and DOHH in different cell lines." (PMID 22927971, 2012).
ischemic stroke (1 paper, 2024). A stroke disorder caused by obstruction of blood flow to the brain, due to thrombotic (local blood clot formation) or embolic (due to a blood clot or other material traveling from another site) event. "Furthermore, it heralds BZ as the first-known allosteric activator of DOHH, laying the groundwork for a novel category of therapeutic agents aimed at combating human ischemic stroke." (PMID 39062499, 2024).
leukemia (1 paper, 2022). A malignant (clonal) hematologic disorder, involving hematopoietic stem cells and characterized by the presence of primitive or atypical myeloid or lymphoid cells in the bone marrow and the blood. "In the leukemia cell line HL-60 with the NRASQ61L mutation and the pancreatic cancer cell line MIA PaCa-2 with the KRASG12C mutation, the mRNA expression of DOHH, HIST1H2AC, and TAF6 were measured with MEK-I treatments." (PMID 36358254, 2022).
non-alcoholic steatohepatitis (1 paper, 2022). "Here, we have found that hepatic DOHH mRNA expression is decreased in patients and mice with non-alcoholic steatohepatitis (NASH), and hepatic cells treated with fatty acids." (PMID 36057633, 2022).
Obesity (1 paper, 2024). Accumulation of substantial excess body fat. "Obesity and DMBA exposure combined decreased the platelet-activating factor acetylhydrolase IB subunit alpha to the greatest level by 5.8-fold and increased deoxyhypusine hydroxylase by 6.1-fold (P < 0.05)." (PMID 37856498, 2024).
Stroke (1 paper, 2024). Sudden impairment of blood flow to a part of the brain due to occlusion or rupture of an artery to the brain. "The DOHH/eIF5A pathway, crucial for nerve regeneration, underscores DOHH’s potential as a therapeutic target for ischemic neuronal injury, despite the lack of selective small molecule DOHH activators for stroke therapy to date." (PMID 39062499, 2024).
visceral leishmaniasis (1 paper, 2012). A severe form of leishmaniasis characterized by irregular bouts of fever, substantial weight loss, swelling of the spleen and liver, and anemia (which may be serious). "We present here the molecular and structural basis of the function of DOHH from the protozoan parasite, Leishmania donovani, which causes visceral leishmaniasis." (PMID 22438895, 2012).
tumor (8 papers, 2012 to 2025). "Several studies demonstrate that CPX exerts its anti-tumor effects by inhibiting the activity of deoxyhypusine hydroxylase (DOHH), one of the key enzymes responsible for eIF5A hypusination." (PMID 41256582, 2025). "Therefore, eIF5A and DOHH have been proposed as targets for anti-tumor and anti-retroviral chemotherapy." (PMID 22438895, 2012). "Finally, qRT-PCR revealed that the abundance of DOHH, P4HA3 and MMP1 were high in tumor cases, indicating the complex mechanism between the high expression of DOHH as a protective factor and the high expression of P4HA3 and MMP1 as the risk factors in the development of GC." (PMID 37957566, 2023). "The results demonstrated that the abundance of DOHH, P4HA3 and MMP1 were higher in tumor cases than normal cases." (PMID 37957566, 2023). "Taken together, these findings suggest that miR-331-3p acts as a tumor suppressor in the brain by coordinately inhibiting expression of multiple target molecules, including NRP-2 and DOHH, leading to reduced GBM cell proliferation and clonogenic growth." (PMID 24142150, 2014). "Expression of DOHH, P4HA3 and MMP1 was assessed with qRT-PCR in tumor cases and the normal cases." (PMID 37957566, 2023). "On the other hand, in the protein expression profile of SSC-2, the neoplastic proliferation of tumor cells was related to the overexpression of PCNA, MPM2, KRAS, STAT3, EGFR, and bFGF and was supported by the overexpression of the protein translation factors eIF5A, DHS, and DOHH compared to SSC-1." (PMID 28789700, 2017).
cancer (6 papers, 2012 to 2025). A tumor composed of atypical neoplastic, often pleomorphic cells that invade other tissues. "Inhibitors of DOHH have been shown to have anti-proliferative effects in mammalian cells, including cancer cells, and lead to cell cycle arrest, indicating the importance of hypusine modification in eukaryotic cells." (PMID 22438895, 2012). "This extracellular aspartate activates the ionotropic N-methyl-D-aspartate receptor in cancer cells, which promotes CREB-dependent expression of deoxyhypusine hydroxylase (DOHH)." (PMID 39743589, 2025). "Gaviscon formulations also revealed the downregulation of various genes such as COL6A2, DOHH, MEX3D, SBNO2, which have roles in cancer or chronic disease progression." (PMID 39409043, 2024). "On the other hand, “hub genes” of four other modules contain POU2F3 (↑), CENPH (↑), PCSK6 (↑) and HERC2 (↑), BCAR3 (↑), DOHH (↑), NLK (↑), SCN2A (↑), CACNA2D3 (↓) and CTNND2 (↓), which were commonly reported related to cancer." (PMID 27602771, 2016).
neurodevelopmental disorder (3 papers, 2022 to 2024). A behavioral and cognitive disorder with onset during the developmental period that involves impaired or aberrant development of intellectual, motor, or social functions. "From whole trio exome sequencing, variants in EIF5A, DHPS, and DOHH genes were identified as the basis of certain rare neurodevelopmental disorders in humans." (PMID 34273022, 2022). "Biallelic variants in DOHH are also associated with a neurodevelopmental disorder and fibroblasts derived from these individuals have decreased DOHH enzyme activity, the accumulation of the intermediate deoxyhypusine eIF5A, and the consequent reduction of eIF5AHyp." (PMID 39125743, 2024). "Furthermore, biallelic DOHH variants also appear to be associated with neurodevelopmental disorder." (PMID 34273022, 2022). "These mice display impairment in growth, lifespan and cognitive functions, reflective of phenotypes of human patients, and may serve as useful tools in the development of chemical or biological therapeutics against neurodevelopmental disorders caused by variants of EIF5A, DHPS, or DOHH." (PMID 34273022, 2022).
infection (2 papers, 2016 to 2025). The state of being infected such as from the introduction of a foreign agent such as serum, vaccine, antigenic substance or organism. "In contrast, overexpression of DOHH completely prevents infection structure formation, pathogenicity in wheat and maize, leads to overproduction of ROS, reduced DON production and increased sexual reproduction." (PMID 27098988, 2016). "DOHH overexpression was associated with less dense mycelia growth and no infection structures forming on the flower leaf surface." (PMID 27098988, 2016). "On the contrary, DOHH overexpression abolished infection symptoms on wheat and maize." (PMID 27098988, 2016). "These analyses showed that depletion of DOHH, PRKRA, SEL1L, UBE2G2, and ZFP36L2 consistently decreased DENV-2 viral protein and RNA levels during infection of Huh7.5.1 cells (respectively)." (PMID 41372121, 2025).
DOHH also shares sentences with these, for which no sentence is quoted: Intellectual disability (2 papers); breast carcinoma (1); pancreatic cancer (1).